SETDB2 (SET domain bifurcated histone lysine methyltransferase 2)
Diseases named in the same sentence as SETDB2 in open-access papers (continued):
Sharing a sentence is not in itself a finding about the gene and the disease.
melanoma (2 papers, 2018 to 2019). A malignant, usually aggressive tumor composed of atypical, neoplastic melanocytes. "During exposure to chemotherapeutics or targeted therapies, we observed the consistent upregulation of SETDB1 and SETDB2 in melanoma, lung and colon cancer-derived cell lines, which indicates a common role for both proteins following drug exposure." (PMID 30850015, 2019). "We have reported that the increase in H3K9me3 is derived from the methyltransferases SETDB1 and SETDB2 following treatment in melanoma, lung, breast and colorectal cancer cell lines, as well as melanoma patient data." (PMID 30850015, 2019). "This draws parallels to a study that showed SETDB1 expression is associated with CDKN2A repression in melanoma, suggesting that SETDB1 and SETDB2 have an important role in controlling the expression of these cell cycle regulators." (PMID 30850015, 2019). "Higher expression of SETDB1, SETDB2 and H3K9me3 was confirmed at the protein level in four IDTC models representative of melanoma, lung and colon cancer." (PMID 29492189, 2018).
viral infection (2 papers, 2015 to 2021). "Regardless, the data presented herein do demonstrate that regulation of NFkB-mediated transcription by SETDB2 following viral infection is likely critical to achieve a homeostatic response to initial or subsequent pathogenic stimuli." (PMID 34479991, 2021). "Since Setdb2 regulates the IFN-I response in viral infection, it is possible the host has evolved to diminish the antiviral response enough to control viral infection, yet prevent secondary complications." (PMID 26709698, 2015). "It is somewhat unexpected that IFN-λ did not upregulate Setdb2 since IFN-I and IFN-III have overlapping roles in viral infection and despite signaling through different receptors, initiate a similar signaling cascade resulting in ISGF3 activation." (PMID 26709698, 2015).
autoimmune disease (1 paper, 2015). A disorder resulting from loss of function or tissue destruction of an organ or multiple organs, arising from humoral or cellular immune responses of the individual to their own tissue constituents. "Together with our findings, these results implicate Setdb2 as a promising therapeutic target in respiratory viral infection and potentially, in secondary complications and autoimmune diseases linked to IFN-I activity." (PMID 26709698, 2015). "The degree of Setdb2 transcription correlated with the concentration of IFN-I, suggesting the extent of expression may be a useful biomarker for determining the severity of infection and autoimmune diseases that result in copious IFN-I production." (PMID 26709698, 2015).
Autoimmunity (1 paper, 2015). The occurrence of an immune reaction against the organism's own cells or tissues. "Therefore, targeting Setdb2 in parallel with anti-TNF-α therapy may be beneficial for repressing exaggerated IFN-I activity in autoimmunity." (PMID 26709698, 2015).
B-cell chronic lymphocytic leukemia (1 paper, 2015). "Setdb2 (SET-domain bifurcated 2) tri-methylates lysine 9 of histone H3 (H3K9me3) to silence gene expression and was first implicated in the induction of B cell chronic lymphocytic leukemia." (PMID 26709698, 2015).
breast tumor (1 paper, 2020). "Silencing SETDB2 also decreased breast tumor initiation and growth in vivo." (PMID 32549764, 2020). "Therefore, SETDB2 plays an essential role in breast tumor initiation and growth in vivo." (PMID 32549764, 2020).
colorectal cancer (1 paper, 2019). A primary or metastatic malignant neoplasm that affects the colon or rectum. "In parallel, another study identified that a frameshift mutation within the mononucleotide repeat of the SETDB2 coding sequence is associated with microsatellite instability (MSI) in colorectal cancer." (PMID 30850015, 2019).
COVID-19 (1 paper, 2021). A disease caused by infection with severe acute respiratory syndrome coronavirus 2. "Together, these results suggest therapeutic targeting of the IFNβ/SETDB2 axis in diabetic patients with COVID-19 may decrease pathologic inflammation." (PMID 34479991, 2021). "SETDB2 protein was also decreased in CD14+ monocytes from COVID-19 (+) patients." (PMID 34479991, 2021). "Together, these results describe a potential mechanism for the increased Mφ-mediated cytokine storm in patients with T2D in response to COVID-19 and suggest that therapeutic targeting of the IFNβ/SETDB2 axis in T2D patients may decrease pathologic inflammation associated with COVID-19." (PMID 34479991, 2021). "The MoMs treated with sera from T2D patients demonstrated decreased SETDB2 expression compared to treatment with serum from nondiabetic patients with COVID-19." (PMID 34479991, 2021).
fatty liver (1 paper, 2022). "Induction of the epigenetic modifier SET domain bifurcated histone lysine methyltransferase 2 (SetDB2) by GR ameliorates fatty liver." (PMID 35614477, 2022).
glioma (1 paper, 2018). A benign or malignant brain and spinal cord tumor that arises from glial cells (astrocytes, oligodendrocytes, ependymal cells). "In contrast, copy number analysis of her DIPG revealed copy number changes frequently seen in gliomas including homozygous loss of RB1, SETDB2, CDKN2A and CDKN2B with no abnormalities in chromosome 17, distinguishing it from the primary medulloblastoma." (PMID 30049282, 2018).
lentivirus infection (1 paper, 2023). Virus diseases caused by the Lentivirus genus. "Meanwhile, we overexpressed the SETDB2 tagged with GFP via lentivirus infection method." (PMID 36504353, 2023).
leukemia (1 paper, 2023). A malignant (clonal) hematologic disorder, involving hematopoietic stem cells and characterized by the presence of primitive or atypical myeloid or lymphoid cells in the bone marrow and the blood. "Previous studies have identified that SETDB2 functions as a transcriptional repressive factor in leukemia, which is consistent with its contributions in multiple homeostatic deseases." (PMID 36504353, 2023).
lung carcinoma (1 paper, 2023). "The wound healing assay showed that depletion of SETDB2 or SNAI3 promoted the migration of lung cancer cells." (PMID 37197420, 2023). "Consistent with the results of bioinformatics analysis, the expression levels of SETDB2 and SNAI3 were higher in BEAS-2B than in lung cancer cell lines." (PMID 37197420, 2023). "The deletions of both SETDB2 and SNAI3 were found to promote proliferation, invasion, and stemness in lung cancer cells." (PMID 37197420, 2023). "In addition, the roles of SETDB2, SNAI3, SCML4, ZNF540, and ETV1 were validated in multiple datasets and human lung cancer cell lines." (PMID 37197420, 2023).
lymphoma (1 paper, 2023). A malignant (clonal) proliferation of B- lymphocytes or T- lymphocytes which involves the lymph nodes, bone marrow and/or extranodal sites. "In addition, SETDB2 was also a glucocorticoid-induced putative epigenetic modifier that promotes the enrichment of glucocorticoid receptor chromatin, and glucocorticoids were found to inhibit the growth of lymphoma." (PMID 37197420, 2023).
Rett syndrome (1 paper, 2023). A severe neurodevelopmental disorder affecting the central nervous system.
type II diabetes (1 paper, 2022). "In pre-diabetic mice that were induced by a high-fat diet that mimics the state of type II diabetes in humans, the INF-I-Setdb2 axis is impaired, thereby reducing Setdb2 and the trimethylation of lysine (H3K9me3)." (PMID 35954275, 2022).
vitiligo (1 paper, 2021). Generalized well circumscribed patches of leukoderma that are generally distributed over symmetric body locations and is due to autoimmune destruction of melanocytes. "In total, we propose the genes NUBPL, PHF11, SETDB2, RCBTB1, PTP4A1, and at a weaker replication level the genes LITAFD, CARHSP1 and OR2C1 as possible candidates for vitiligo-like depigmentation in grey horses." (PMID 34696794, 2021).
cancer (11 papers, 2016 to 2024). A tumor composed of atypical neoplastic, often pleomorphic cells that invade other tissues. "Regarding the three genes (WWOX, CADM1 and CCDC80) detected as SETDB2 target genes in our study, their loss or reduced expression has been reported in various cancers." (PMID 27572307, 2016). "In the context of cancer, SETDB2 is often implicated to be involved in tumorigenesis; its overexpression can lead to abnormal H3K9 trimethylation, which results in the silencing of tumor suppressor genes and the promotion of cancer cell proliferation and survival." (PMID 39765675, 2024). "In cancer research, SETDB2 plays oncogenic roles, involved in cell cycle dysregulation, cancer stem cell maintenance, and metastasis." (PMID 38151757, 2024). "Among them, PRDM16, SETDB2, SGF29, and ZCWPW2 were protective genes and were all downregulated in the tumor samples, while the others were enriched in the cancer tissues and were associated with poor prognosis." (PMID 36263018, 2022). "The majority of studies investigating the function of SETDB2 have often focused on general developmental biology, while its role in cancer is very much an emerging field." (PMID 30850015, 2019). "In contrast to family members SUV39H1/2 and G9a, SETDB2 is relatively unexplored and remains poorly characterised in cancer." (PMID 30850015, 2019). "Microarray, qRT-PCR and protein expression data confirmed the up-regulation of histone methyltransferases (SETDB1 and SETDB2) which contribute to the accumulation of H3K9me3 concomitantly in the different cancer types." (PMID 29492189, 2018). "Further studies are warranted to know whether the oncogenic characteristics of SETDB1 and SETDB2 are universal for all cancers or just specific to particular cancer type." (PMID 31245293, 2019). "Cancer cells in proliferative phases are largely heterogeneous and have varying needs for different cancer types, which could explain the differences in SETDB1 and SETDB2 expression for the progression of different cancers." (PMID 30850015, 2019). "Additionally, the potential mechanisms by which SETDB2 can exert the same multifaceted effects on cancer development have not been explored and will be the major focus of the following chapter." (PMID 30850015, 2019). "Because SETDB2 knockdown led to significant inhibition of cell growth, migration and invasion, we further selected six tumor- or differentiation-related genes (WWOX, CADM1/TSLC1, CCDC80, NDRG1, CA9 and FZD9) that have been reported to show altered expression in several cancers including GCs." (PMID 27572307, 2016). "Furthermore, there has not been reported the evidence presented of SETDB2 alterations in cancers." (PMID 27572307, 2016).
tumor (8 papers, 2016 to 2023). "On the other hand, SETDB2 overexpression is associated with poor prognoses and tumour progression in gastric cancer through H3K9me3-mediated silencing of tumour suppressor genes WWOX and CADM1." (PMID 30850015, 2019). "In this study, we first demonstrated that SETDB2 could link the associations between H3K9me3 with oxidative stress in tumor progression." (PMID 36504353, 2023). "Additionally, a recent study found low SETDB2 expression was associated with metastatic spread of late-stage renal cell tumours further suggesting a tumour-suppressive role." (PMID 30850015, 2019). "How to target SETDB2 to elevate its expression levels would receive multiple efficacy, including suppression of tumor growth and improvement of chemotherapy sensitivity in LUAD." (PMID 36504353, 2023). "In summary, this study identified that SETDB2 expressed lowly and functioned as a tumor suppressor in LUAD." (PMID 36504353, 2023). "The SET domain bifurcated histone lysine methyltransferase 2 (SETDB2) mediated the formation of repressive mark trimethylated H3K9 (H3K9me3), which was reported to be associated with tumor‐related phenotypes." (PMID 36504353, 2023). "SETDB2 negatively regulates NRF2 signaling to modulate tumor progression, which creates a therapeutic vulnerability in LUAD." (PMID 36504353, 2023). "We found that SETDB2 expression is decreased in tumor samples versus normal tissues in TCGA‐LUAD cohort, LUAD‐EAS cohort, GSE72094 dataset, and independent Soochow‐LUAD dataset." (PMID 36504353, 2023). "In this study, we found that SETDB2 was a tumor suppressor in LUAD, which expressed lowly in tumor samples." (PMID 36504353, 2023). "In our study, SETDB2 was found to be downregulated in tumor samples, and its higher expression level predicted a better prognosis, indicating that it is a tumor suppressor gene." (PMID 36263018, 2022). "The histone modifier SETDB2 was found to modulate adaptative resistance mechanisms in tumor development and in macrophage plasticity in inflammatory processes by regulating genomic stability and/or H3K9me3-mediated silencing of gene transcription." (PMID 34696794, 2021). "The highlighted genes PHF11, SETDB2, CARHSP1 and LITAFD, are associated with the innate immune system, while the genes RCBTB1, LITAFD, NUBPL, PTP4A1, play a role in tumor suppression and metastasis." (PMID 34696794, 2021). "Compared with the NC group, the SETDB2-knockdown group showed a significant delay in tumor growth as well as smaller tumor size, volume and weight." (PMID 32549764, 2020). "This apparent context-dependent role for SETDB2 in tumour development is likely due to its regulation of genomic stability and/or H3K9me3-mediated silencing." (PMID 30850015, 2019). "Overexpressed SETDB2 could inhibit tumor progression in vivo and further render LUAD cells sensitive to chemotherapy." (PMID 36504353, 2023). "However, SETDB2‐OE significantly suppressed the tumor volumes and exhibited profound synergistic effect with cisplatin treatment, as indicated by tumor volumes." (PMID 36504353, 2023). "Lastly, the NRF2‐driving tumor‐promoting abilities could be largely suppressed via ectopic overexpression of SETDB2, as indicated by the CCK‐8 assays." (PMID 36504353, 2023). "Taken together, SETDB2 interacts with ΔNp63α, methylates and stabilizes the ΔNp63α protein to upregulate the Hedgehog pathway-associated genes CXCR4, PTCH1 and GLI2, which promote stem cell maintenance, tumor initiation and growth." (PMID 32549764, 2020). "We confirmed the speculation in the tissues of patients with LUAD, where SETDB2 protein levels were significantly downregulated in high‐grade LUAD tumor sections compared with low‐grade samples or normal lung tissues via immunohistochemistry (IHC) staining method." (PMID 36504353, 2023). "NC or SETDB2-knockdown SUM159PT cells were inoculated into the mammary glands of nude mice, and tumor growth was monitored for up to 9 weeks." (PMID 32549764, 2020).
tumor (continued). "Collectively, our findings indicated that SETDB2 functions as a tumor suppressor in LUAD and SETDB2 inhibition could promote the capacities of cell proliferation, migration, and stemness." (PMID 36504353, 2023). "SETDB2 expression was upregulated in M1 macrophages, which killed tumor cells, but not in M2 macrophages, which promoted tumor growth, invasion, and metastasis." (PMID 37197420, 2023).
infection (5 papers, 2015 to 2023). The state of being infected such as from the introduction of a foreign agent such as serum, vaccine, antigenic substance or organism. "This demonstrated decreased SETDB2 at inflammatory gene promoters both following MHV-A59 infection and in SETDB2 myeloid cell−deficient BMDMs both before and after MHV-A59 infection." (PMID 34479991, 2021). "Down-regulation of SETDB2 following infection led to the loss of H3K9 trimethylation at NFkB binding sites on the promoters of inflammatory genes, leading to increased transcription." (PMID 34479991, 2021). "Since the selectivity of the identified Setdb2-regulated antiviral genes is not limited to IAV, it is plausible that Setdb2 controls the resolution of infection caused by other viral pathogens." (PMID 26709698, 2015). "We suggest that upon HMPV infection of human macrophages a mechanism of repressive mark gain additional to the previously identified SETDB2-dependent mechanism is initiated that results in increased H3K27me3 at the IL-1β promoter." (PMID 37435074, 2023). "In conclusion, we identified that SETDB2 is a regulator of Mφ-mediated inflammation during coronavirus infection, and that decreases in Setdb2 following infection lead to unrestricted transcription of inflammatory cytokines." (PMID 34479991, 2021). "The Histone Methyltransferase SETDB2 Is Decreased in Human and Murine Mφs following Infection with SARS-CoV-2 and MHV-A59." (PMID 34479991, 2021). "Decreased H3K9me3 was found on the NFkB binding promoters of inflammatory genes following infection, corresponding to the decreased Setdb2 expression seen after MHV-A59 infection." (PMID 34479991, 2021). "On day 4 post-infection, a 90% reduction in Setdb2 transcript was observed in CD11b+ cells from Stat1-/- lungs relative to control lungs." (PMID 26709698, 2015). "Since exposure to IAV triggers robust IFN-I production, we next characterized Setdb2 expression in a murine model of infection." (PMID 26709698, 2015). "On day 4 post-infection, enhanced expression of Ifnb1 correlated with a 11-fold increase in Setdb2 transcript when normalized to uninfected lungs (11.0 ± 1.38 vs. 1.0 ± 0.43; p<0.001)." (PMID 26709698, 2015). "On day 4 post-infection, the proportion of alveolar Mφ expressing Setdb2 nearly doubled, with greater than 70% expressing lacZ (31.3 ± 1.74% vs. 74.6 ± 2.69%; p<0.001)." (PMID 26709698, 2015). "In the lungs, alveolar Mφ expressed the highest level of Setdb2, with greater than 70% lacZ positive on day 4 post-infection." (PMID 26709698, 2015). "In addition, Setdb2 was upregulated in the spleen following infection (7.38 ± 0.19% vs. 25.9 ± 2.37%; p<0.001)." (PMID 26709698, 2015). "Thus, by regulating the expression of specific ISGs, Setdb2 dictated the severity of infection." (PMID 26709698, 2015). "Similar to our previous work with wound Mφs showing a decrease of SETDB2 in T2D, we found that Setdb2 in BMDMs was decreased in DIO BMDMs compared to ND controls both at baseline and after MHV-A59 infection." (PMID 34479991, 2021). "Furthermore, SETDB2-ChIP demonstrated decreased SETDB2 at inflammatory gene promoters in DIO BMDMs compared to controls both before and after infection, whereas, after MHV-A59 infection, SETDB2 was undetectable in DIO BMDMs." (PMID 34479991, 2021). "Comparing the most modulated genes between activated and non-activated cells at 24h post-infection, we observed that SETDB2 and RPS6KA3 were up-regulated in both conditions, however in activated cells the modulation occurred to a greater extent." (PMID 25875202, 2015). "While the number of both T cell populations were similar in control and knockout lungs on day 8 post-infection, a 2-fold increase in CD8+ T cells (6.54 ± 1.05 x 105 vs. 11.80 ± 1.47 x 105; p<0.01) was observed on day 10 in mice lacking Setdb2." (PMID 26709698, 2015).
bacterial infection (3 papers, 2016 to 2023). "For instance, Setdb2, the family member most closely related to Setdb1, mediates virus-induced susceptibility to secondary bacterial infection by regulating CXCL1 transcription." (PMID 27349785, 2016). "Setdb2 is upregulated and induces the repressive H3K9me3 of at Cxcl1 promoter, leading to reduced neutrophil infiltration and attenuated host defense against secondary bacterial infection." (PMID 37143582, 2023).
metabolic disorders (1 paper, 2025). "This opens up the possibility that targeting Setdb2’s enzymatic vs. scaffold activity may result in context-dependent potential therapeutic targeting of the divergent pathways in inflammatory or metabolic disorders." (PMID 40502770, 2025).